TERT (telomerase reverse transcriptase)
Diseases named in the same sentence as TERT in open-access papers (continued):
Sharing a sentence is not in itself a finding about the gene and the disease.
cancer (continued). "During the last two decades, substantial advances have been made in understanding the molecular mechanisms causing TERT upregulation in cancer." (PMID 31757062, 2019). "In this context, we developed pDUV5, a DNA plasmid encoding the canine TERT equivalent to INVAC-1 as an immunotherapeutic agent to fight dog cancers." (PMID 31164958, 2019). "The activation of TERT in cancer was thought to be caused by point mutations in its promoter region." (PMID 31235699, 2019). "The result demonstrated that the TERT rs10069690 polymorphism was found to be associated with a significantly increased cancer risk overall." (PMID 31454181, 2019). "A growing number of epidemiological studies have provided evidence that TERT polymorphisms contribute to cancer development." (PMID 31454181, 2019). "In cancer cells carrying heterozygous TERT promoter mutations, the mutant promoter recruits GABPA and exhibits the H3K4me2/3 mark of active chromatin." (PMID 31285550, 2019). "This transcription factor directly recruits DNA polymerase II and it provides a possible mechanism for the activation of TERT caused by promoter mutations across multiple cancer types." (PMID 30795542, 2019). "In general, TERT promoter mutations appear to mainly represent characteristic alterations of adult cancers, and their occurrence is strongly correlated with age." (PMID 31757062, 2019). "Based on the data from all 45 studies, we found a significant increased cancer risk for the TERT rs10069690 under a per‐allele risk analysis (OR = 1.09, 95% CI: 1.06–1.12, p < .001), with a statistical power of 100%." (PMID 31454181, 2019). "Mutations in the coding regions of TERT can affect telomerase activity and telomere length, and generate severe clinical phenotypes, including a substantive increase in cancer frequency." (PMID 31454181, 2019). "Since the first report of highly recurrent mutations in the TERT promoter region in melanoma, their presence has been reported in numerous cancers." (PMID 31757062, 2019). "Of note, the discovery of SSV-mediated deregulation of TERT in solid tumors was first made in the chRCC cancer type, though the associations involving DNA methylation had not previously been made." (PMID 31610796, 2019). "Increased telomerase activity has been described in a high percentage of tumors and transcriptional alteration of the TERT gene is the major cause of its cancer-specific activation." (PMID 30884806, 2019). "High TERT levels in cancer tissues were independently associated with worse response to therapy (odds ratio [OR]:6.26), regional failure (hazard ratio [HR]:5.75), progression (HR:2.12), and death (HR:3.53)." (PMID 31772219, 2019). "This demonstrates that integrating multi-omics molecular information associated with TERT yields two cancer subtypes with more discrimination in telomerase activity and patient survival compared with those using TERThigh and TERTlow information only." (PMID 31179925, 2019). "Mutation of the proximal promoter of the human TERT gene is now considered to be the most common noncoding mutation in cancer." (PMID 31159515, 2019). "In this study, BRAF V600E, RET/PTC1 rearrangement, and TERT promoter mutations were found to be associated with aggressive cancers 65.7% of the time." (PMID 31623671, 2019). "Alteration in TERT expression and/or activity has been reported in many cancers and associated with increased aggressiveness." (PMID 31200515, 2019). "The methylation status of the chromatin surrounding TERT promoter is also affected by the presence of cancer-associated mutations reflecting the transcriptional activity of this region." (PMID 31200515, 2019). "In conclusion, our data suggest that concomitant BRAFV600E and TERT promoter mutations synergistically support cancer cell proliferation and immortalization." (PMID 31391125, 2019). "A survey of 1,230 samples of 60 different cancer types revealed tumors with low (<15%) and high (≥15%) frequencies of TERT promoter mutations." (PMID 31757062, 2019).
cancer (continued). "Our findings are consistent with previous genome wide association studies stating the role of TERT gene in different cancers at different ethnicities." (PMID 31126249, 2019). "A meta-analysis indicates that TERT promoter mutations are associated with patient age, gender and distant metastasis in individuals with cancers." (PMID 30934988, 2019). "The SNPs that modulate TERT transcriptional capacity are not restricted to the TERTp: as GWA studies have demonstrated, there are TERT germline genetic variations that lead to an increased risk of developing several cancer types." (PMID 29751586, 2018). "One such example is the TERT gene, which encodes telomerase reverse transcriptase, and is often found to be overexpressed in cancer cells." (PMID 29677098, 2018). "Recently, two recurrent mutations within the TERT promoter have been identified and associated with aggressiveness and poor prognosis in many types of cancer." (PMID 30466442, 2018). "Mutations in the coding regions of telomerase genes are very rare in cancer, however, somatic mutations in the promotor region of the TERT gene has been reported in the context of several cancer types." (PMID 29536006, 2018). "Summary of meta-analysis of association between the TERT variant rs2736098 polymorphisms and cancer risk." (PMID 29695979, 2018). "Germline mutations in the TERT gene lead to dyskeratosis congenita, a disorder characterized by cancer susceptibility due to telomeres shortening." (PMID 29641446, 2018). "Incessant telomere synthesis in cancer cells depends on specific mutations in the TERT promoter, enabling its activation by transcription factors ETS1 and p52." (PMID 30093619, 2018). "Previous studies reached paradoxical conclusions regarding the association between TERT rs2736098 polymorphisms and cancer risk." (PMID 29695979, 2018). "Two highly recurrent, but mutually exclusive, cancer-specific TERT promoter mutations identified recently have been shown to cause reactivation of TERT promoter in cancers." (PMID 30093619, 2018). "As an effect of this binding, the promoter locus was changed into an open, active chromatin region, eventually enhancing TERT expression which has been widely associated with cancer development." (PMID 29458419, 2018). "TERT-locus single nucleotide polymorphisms (SNPs), located on chromosome 5p15.33, have reportedly been associated with the risk of several types of human cancers." (PMID 29534075, 2018). "Recurrent mutations at two hotspot regions (C228T and C250T) in the TERT promoter have been reported in various types of cancers, and a recent report outlined the mechanism that TERT promoter mutations reactivate TERT expression." (PMID 29693015, 2018). "This identified 160 significant non-coding elements, including the TERT promoter, a well-known non-coding driver element, as well as elements associated with known cancer genes and regulatory genes (e.g., PAX5, TOX3, PCF11, MAPRE3)." (PMID 29354286, 2018). "The affected genes included TERT, which plays a significant role in cancer cell immortality, and the mutation in its promoter region which is one of the most frequent alterations in HCC." (PMID 30016933, 2018). "We assessed the functional significance of recurrent noncoding mutations identified in cancer, using TERT promoter mutations as the representative example." (PMID 29390075, 2018). "Consistent with earlier pan-cancer studies, mutational hotspots were also identified near TERT and PLEKHS1 genes in this study." (PMID 30577431, 2018). "Significant statistics were observed for the association between the TERT rs2853669 polymorphism and cancer susceptibility in the variant CT homozygote compared with the TT wild-type homozygote model." (PMID 29534075, 2018).
cancer (continued). "Several single nucleotide polymorphisms (SNPs) are present within the TERT locus and some have been associated with the risk of cancer." (PMID 29562930, 2018). "The association between the human telomerase reverse transcriptase (TERT) gene variant rs2736098 polymorphisms and cancer predisposition remain inconclusive." (PMID 29695979, 2018). "For source of control, however, only one homozygote comparison (CT vs. TT: OR = 1.124, 95% CI = 1.026–1.230; P = 0.012) in the population-based control source showed a significant association between the TERT rs2853669 polymorphism and cancer risk." (PMID 29534075, 2018). "Further investigations reveal that the activation of TERT expression can be allele-specific in cancer cells, which are under pressure to maintain active alleles protected from DNA methylation." (PMID 29439385, 2018). "A number of studies have also reported that variants of TERT gene are associated with a significantly higher susceptibility to several cancers." (PMID 29507683, 2018). "Summary of pooled ORs in the stratified analysis association between TERT rs2853669 and cancer risk." (PMID 29534075, 2018). "The role of TERT –245T>C polymorphism in cancer is debated, and research on this topic has provided controversial result." (PMID 29464027, 2018). "Further investigation revealed that these somatic mutations were associated with an allele-specific switch to an active transcriptional state and monoallelic TERT expression of the allele containing the TERT promoter mutation across multiple human cancers." (PMID 29439385, 2018). "Most recently, common TERT promoter mutations are shown to be associated with allele-specific hypomethylation of the TERT promoter in cancer cells with TERT expression." (PMID 29439385, 2018). "In this study, we observed that the chicken TERT promoter is significantly methylated in unoccupied alleles across normal and cancer tissues." (PMID 29439385, 2018). "Yet, another locus replicating in our study that is associated with several types of cancer is the TERT locus at 5p15.33." (PMID 29266682, 2018). "One of these, TERT, is the only gene identified as a cancer driver because of a recurrently non-coding mutation in its promoter region." (PMID 29855388, 2018). "An increasing number of human cancer types exhibit mutations in the TERT promoter that lead to upregulated telomerase activity or mutations within shelterin components such as POT1, both of which often result in a longer average telomere length." (PMID 29335368, 2018). "Herein, we investigated the frequency of TERT mutations in a seriesof Brazilian patients with colorectal precursor and cancer lesions." (PMID 29473934, 2018). "In renal cell cancer, the AA genotype of TERT rs2736098 is associated with increased cancer susceptibility and decreased telomere length compared with the GG genotype." (PMID 29695979, 2018). "Many studies have assessed the relationship between TERT gene polymorphisms and cancer susceptibility; however, studies have yet to reach a consensus." (PMID 29695979, 2018). "Recurrent point mutations in the promoter of TERT have been identified in a range of cancers, with an overall frequency of around 19%, although some cancers show a higher incidence." (PMID 29415479, 2018). "Additional cancer genes recurrently mutated in adenomyoepitheliomas included TERT (4/31, 13%, all hotspot promoter mutations) and PRKAR1A (2/31, 6%)." (PMID 29739933, 2018). "The unique oncogene duet of coexisting BRAF V600E and TERT promoter mutations is an important recent discovery in human cancer as a robust genetic background for the development of the most aggressive disease in several cancers." (PMID 29422527, 2018). "TERT is commonly overexpressed in cancer cells, indicating genomic instability caused by telomerase activation, and telomere length change is associated with cancer risk and prognosis." (PMID 29695979, 2018).
cancer (continued). "The evaluation of hotspot TERT promoter mutations showed thatall precursor and cancer lesions (123 samples), which included 45 adenoma polyps, 15serrated polyps, 22 hyperplastic polyps and 41 adenocarcinomas, were wild-type." (PMID 29473934, 2018). "For example, telomerase (TERT) activation is a fundamental step in tumorigenesis, and many mutations in the TERT promoter are found in over 50 cancer types; additionally, TERT mutations are the most common mutations in many cancers." (PMID 29703163, 2018). "A fundamental question remains unanswered, however, as to how this oncogene duet cooperates mechanistically, particularly with respect to how BRAF V600E is functionally linked to the mutant TERT, in cooperatively driving human cancer aggressiveness." (PMID 29422527, 2018). "The rs2736098 (G > A) polymorphism, located in the second exon of TERT, is one of the most commonly investigated SNPs in the TERT gene, and its association with the risk of cancer was reported in various malignancies." (PMID 29695979, 2018). "In some cancers, TERT upregulation occurs as a result of point mutations at hotspots in the TERT promoter, which allow for the binding of new transcription factors, such as the Myc or Ets transcription factors." (PMID 29874793, 2018). "Mutations in the TERT promoter were detected in 57% of the 175 urinary cell samples from the patients who developed cancer during the study interval (95% CI, 49% to 64%)." (PMID 29557778, 2018). "The two cytosine to thymidine single-point mutations in the TERT proximal promoter (− 146 and − 124 bp from the translation start site), recurrent in several cancers, were found to create a de novo consensus binding motif for ETS transcription factor family." (PMID 29458419, 2018). "The association between TERT rs2853669 and cancer risk has since been studied in multiple ethnicities and populations with inclusive results." (PMID 29534075, 2018). "The meta-analysis of cancer studies showed a pooled positive correlation with the TERT allele that is known to cause longer telomeres." (PMID 29536006, 2018). "Because of its close association with telomere length, single nucleotide polymorphisms (SNPs) in TERT have been suggested as potential target genes for cancer therapy." (PMID 29695979, 2018). "Perhaps in some human cancers, there is a decrease in TERT promoter methylation in the activated allele while on average there was an increase in methylation across the population of alleles when compared to corresponding normal tissue." (PMID 29439385, 2018). "In total, fifteen case-control studies were enrolled, including 9,157 cases and 11,073 controls, to explore the relationship between the TERT rs2853669 polymorphism and cancer risk." (PMID 29534075, 2018). "In conclusion, the results of this meta-analysis indicated significant associations between the TERT variant rs2736098 polymorphisms and cancer risk." (PMID 29695979, 2018). "After many types of research focusing on the mutations rate in malignant tumors, the main role of TERT promoter mutations has been changed to the preoperative diagnosis and prognosis of TC, according to their high prevalence in aggressive TC." (PMID 30024548, 2018). "A systematic search of studies on the association of TERT rs2853669 polymorphism with all types of cancer was conducted in PubMed, Embase and Cochrane Library." (PMID 29534075, 2018). "The unique oncogene duet of coexisting BRAF V600E and TERT promoter mutations are widely found to be a robust genetic background promoting human cancer aggressiveness, but the mechanism is unclear." (PMID 29422527, 2018). "Many cancers also exhibit mutations in the TERT promoter locus, which increase transcriptional activation of this gene." (PMID 28106782, 2017). "Comparatively, mutations within the TERT promoter were recently recognized to induce activation of telomerase activity in multiple cancers." (PMID 28427205, 2017).
cancer (continued). "Nevertheless, patients with TERT promoter mutation-positive HCCs have lower frequencies of cancer susceptibility genotypes rs2736098_TT and rs2736100_CC." (PMID 28416747, 2017). "It has been documented that the frequency of TERT promoter mutations varies significantly from cancer to cancer, but the underlying mechanism is unclear." (PMID 28416747, 2017). "Overexpression of telomerase subunit TERT can decrease oxidative stress in cancer cell lines, whereas TERT-deficient HSCs are characterized by ROS impairment and functional defects." (PMID 28928745, 2017). "Human leukocyte antigen (HLA) typing revealed HLA-A*0201 homozygosity, which is the prevalent HLA class I allele that has been used to develop universal cancer vaccine targeting TERT-derived peptides." (PMID 28245875, 2017). "All but two cancers found positive for TERT promoter mutations (5/7) also harbored another RAS or BRAF gene mutation." (PMID 29085338, 2017). "Of note, it should also be pointed out that both rs2736100_CC and rs2736098_TT genotypes increase cancer risk, despite their opposite impacts on TERT transcription and telomere length regulation." (PMID 28416747, 2017). "The TERT gene is important to maintain chromosomal stability and mutations within its promoter region exist in several human cancers." (PMID 28881610, 2017). "The high frequency of TERT promoter mutations in a multitude of advanced cancers implicates their role as a key mechanism of telomerase reactivation." (PMID 28264499, 2017). "More and more epidemiological studies were accessible regarding the association between the TERT rs2736098 polymorphism and cancer risk, yet conflicting conclusions remain." (PMID 29221218, 2017). "TERT expression is often increased in cancer due to point mutations in TERT’s promoter region, resulting in the recruitment of multiple different potential transcriptions factors that upregulate TERT and thus increase telomerase activity." (PMID 28218725, 2017). "The promoter of the TERT gene is known to play an important role in telomerase expression, and cancers with TERT promoter mutations have been shown to exhibit an elevated expression of the TERT gene." (PMID 28362259, 2017). "In all, we found a significant relationship between TERT rs2736098 and cancer risk in the pooled analysis under all the five-genetic model, except for heterozygous model." (PMID 29221218, 2017). "The obtained results suggested that there exists a significant relationship between TERT rs2736098 and cancer risk." (PMID 29221218, 2017). "Numerous studies have investigated the role of TERT gene rs2746098 polymorphism in the contributions to cancer risk." (PMID 29221218, 2017). "After validating μ-cisTarget on the TAL1, LMO1, and TERT mutations, we analyzed ten widely used cancer cell lines as a discovery set." (PMID 28854983, 2017). "The TERT promoter mutation ddPCR assay offers a sensitive test for molecular analysis of melanoma tumors and ctDNA, with the potential to be applied to other cancers." (PMID 29108273, 2017). "In this meta-analysis, we attempted to settle down the debate about the role of TERT rs2736098 in cancer risk." (PMID 29221218, 2017). "Genetic variations in TERT and other genes involved in telomere biology as well as their regulatory elements can substantially impact cancer susceptibility." (PMID 28427205, 2017). "Identification of the lysine 639 on Sp1 as a specific target of TIP60 offers the possibility of a diagnostic tool for TERT-driven cancers." (PMID 29045464, 2017). "Regarding TERT rs2736100 polymorphism, the association between this SNP and cancer risks was also reported in previous case- control and meta- analysis studies." (PMID 28423629, 2017). "The TERT rs2736100 polymorphism, localized in the second intron of the TERT gene, has been wildly studied with respect to cancer risk." (PMID 28418878, 2017).